RHOA (ras homolog family member A)
Diseases named in the same sentence as RHOA in open-access papers (continued):
Sharing a sentence is not in itself a finding about the gene and the disease.
melanoma (continued). "Here, we show that RhoA, BRAF and Mitogen Activating Protein Kinase pathways are involved in the positive transcriptional regulation of CD70 expression in melanomas." (PMID 26828592, 2016). "We used a siRNA strategy to reduce RhoA, RhoB, or RhoC expression in CD70+ LB1319-MEL human melanoma cells." (PMID 26828592, 2016). "In a previous study, we showed that RhoA GTPase and its effectors ROCK downregulate membrane FasL expression in B16F10 melanoma cells in vitro." (PMID 26236689, 2015). "We have previously shown that RhoA GTPase and its effector ROCK negatively control FasL membrane expression in murine melanoma B16F10 cells." (PMID 26236689, 2015). "Knockdown of miR-33b in cordycepin-treated Lu1205 and A375 melanoma cells increased the levels of phosphorylated FAK, Src, and MLC and RhoA-GTP." (PMID 25868853, 2015). "Inhibition of RhoA in melanoma cells has shown to increase rate of anoikis by inactivating FAK and reducing ITGA5 integrin expression in melanoma cells." (PMID 26587543, 2015). "In the current study, we demonstrated that HMGA2 was involved in cordycepin-mediated suppression of late-stage melanoma metastasis through modulation of the activation status of FAK, Src, MLC and RhoA and expression of MMPs." (PMID 25868853, 2015). "Rac1 activation through ROCK inhibition in MCF-7 cells was expected, as ROCK antagonizes RhoA-dependent Rac1 activation in fibroblasts, and Rac inactivation through ROCK is occurs via FilGAP phosphorylation or ARHGAP22 activation in melanoma cells." (PMID 24523903, 2014). "Knockdown of Vav1 by RNAi in melanoma cells led to impaired activation of the Jak/Vav1/RhoGTPases (Rac1 and RhoA) pathway, blocking up-regulation of MT1-MMP by CXCL12, a mechanism that contributes to melanoma cell invasion." (PMID 25313137, 2014). "Additionally, NAC promoted invasive properties of melanoma cells by increasing GSH levels and activating Ras homolog family member A (RhoA)." (PMID 41516400, 2026). "A second paper from this group demonstrated that s-μg obstructs focal adhesions, leading to inhibition of FAK and RhoA signaling, and blockage of the mTORC1 pathway, which eventually results in activation of the AMPK pathway and reduced melanoma cell proliferation and metastasis." (PMID 37048115, 2023). "However, both RHO GTPase arms cross-talk with pro-survival/proliferation signalling, given that RHOA-ROCK were shown to cooperate with pro-survival mediators (such as STAT3 and NF-κB in melanoma cells) while RAC1 activated PI3K-AKT in breast cancer cells." (PMID 35159327, 2022). "RhoA may also act through downstream effectors like YAP1, which has already been shown to confer resistance to BRAF/MEK inhibitor treatment in melanoma." (PMID 33807778, 2021). "Melanoma cells exposed to a clinostat exhibited fewer focal adhesions and altered cytoskeleton and nuclear positioning, leading to enhanced cell apoptosis via suppressing the FAK/RhoA-regulated mTORC1/NF-κB and ERK1/2 pathways." (PMID 34445479, 2021). "Given that this balance is regulated by levels of active RAC and RHOA, it is not surprising that these two Rho GTPases are involved during melanoma progression." (PMID 34503171, 2021). "Particularly, we further revealed that ropivacaine inhibited migration mainly via suppressing RhoA whereas induced apoptosis mainly via inhibiting Ras in melanoma cells, and furthermore that this was not dependent on VGSC." (PMID 32085741, 2020). "We found that VGSC activator vetratridine at concentrations that abolished amide-linked local anesthesia-induced membrane depolarization did not affect melanoma cell RhoA, Rac1 or Ras activity." (PMID 32085741, 2020). "In addition, miR-23a has been identified as a negative regulator of ATG12, while ATG12 regulated melanoma cell invasion and migration through AMP-activated protein kinase-RAS homolog family member A (AMPK-RhoA) pathway." (PMID 32340261, 2020).
melanoma (continued). "In contrast, bupivacaine which did not display inhibitory effects on melanoma cells did not affect RhoA, Rac1 and Ras activities, suggesting the specific inhibitory effects of ropivacaine on these small GTPases." (PMID 32085741, 2020). "Similarly, high levels of RhoA signaling, coupled with elevated activation of MRTFA and YAP1, promotes BRAFi resistance in dedifferentiated melanoma cell lines characterized by a decreased expression of melanocyte lineage genes." (PMID 32466585, 2020). "Intravenous injection of B16-F10 melanoma cells overexpressing RhoB, but not RhoA, inhibited colonization of melanoma cells in the lung in their mouse model." (PMID 29385717, 2018). "While promoting activity of RhoA, IQGAP1 may also decrease activity of Rac1 in the cell tail during melanoma migration, which may require interactions with C-terminal domains of IQGAP1." (PMID 29240845, 2017). "RhoA silencing can lead to the expression decline of CD70, while the overexpression of RhoA can induce the significant increase of CD70 expression, suggesting that RhoA may be related to the inhibition of melanoma." (PMID 28404912, 2017). "Importantly, HT168-M1 human melanoma cells with high baseline migration capacity showed increased HIF-1α and small GTPases expression, RhoA activation and migration under hypoxia." (PMID 28562340, 2017). "Butyrate, TSA and vorinostat significantly inhibit the activity of RhoA in melanoma cells, whereas valproic acid does not produce significant changes in this parameter." (PMID 27549189, 2016). "Here, using three other human melanoma cell lines we have shown that RhoA, rather than RhoC, controls the migration and invasive capacities of melanoma cells through its positive regulation of melanoma-expressed CD70." (PMID 26828592, 2016). "Here we have shown that RhoA and MAPK pathway cross-talk to regulate melanoma-expressed CD70." (PMID 26828592, 2016). "Interestingly, inhibition of ROCK (using Y27632), a downstream target of RHOA signalling, also induces CDKN1A in melanoma, and ROCK1 has been identified as a potential candidate for combinatorial therapy with BRAF inhibitors." (PMID 27835901, 2016). "Unlike the overexpression of Rac1, RhoA activity in B16 melanoma cells exhibited no significant change in the short period after narrow-band UVB irradiation, although a delayed elevation was observed." (PMID 24649261, 2013). "The finding that Rnd3 promotes migration of cortical neurons through inhibition of RhoA activity was not surprising, because it uses the same mechanism to regulate the migration of fibroblasts, melanoma cells, and other cell types in culture." (PMID 21435554, 2011). "Conversely, melanoma cell movement in the absence of BRAF inhibition was unaffected by RND3 expression or RHOA depletion." (PMID 21917148, 2011). "The current study identifies novel roles for RND3 and RHOA in the movement but not growth or survival of melanoma cells treated with BRAF inhibitors." (PMID 21917148, 2011). "Both Wnt1 and Wnt3a have been shown to activate RhoA, whereas the non-canonical Wnt5a promotes melanoma migration via RhoB." (PMID 19473496, 2009). "Recent studies have revealed that, in melanoma, the Raf/MEK/ERK inhibitor avutometinib downregulates RhoE, thereby relieving its inhibitory effect on the ROCK pathway, leading to activation of the RhoA/ROCK axis and subsequent upregulation of p-FAK, ultimately contributing to drug resistance." (PMID 41232667, 2025). "One study found that in melanoma cells, lidocaine and ropivacaine, but not bupivacaine, decreased Ras, RhoA, and Rac1 expression, and augmented the antimigratory, antiproliferative and pro-apoptotic effects of the chemotherapeutic agents vemurafenib and dacarbazine when used in combination." (PMID 38741694, 2024). "Mechanistic investigation further revealed that the RhoA-myosin II pathway may mediate YAP enhanced melanoma negative durotaxis." (PMID 36428972, 2022).
melanoma (continued). "Collectively, our data suggest that CH could be a powerful tool to counteract the amoeboid motility and the metastatic dissemination of melanoma cells by affecting the mitochondrial-mediated activation of AMPK and consequently blocking the RhoA/ROCK-dependent amoeboid phenotype." (PMID 34298765, 2021). "Additionally, ropivacaine decreased RhoA and Ras activities to a larger extent than Rac1 activity, suggesting that the dominant effects of ropivacaine are inhibition of RhoA and Ras rather than Rac1 in melanoma cells." (PMID 32085741, 2020). "The lack of changes in Ras and RhoA activities in melanoma cells following bupivacaine treatment may also explain their unchanged migration, growth and survival behaviours." (PMID 32085741, 2020). "Since MARCKS phosphorylation is important for the control of actin dynamics, our novel observations of PKC and RhoA-ROCK signaling being involved in melanoma cell invasion mediated by WNT5A-induced MARCKS phosphorylation, suggest the importance of these signaling pathways in melanoma." (PMID 32033033, 2020). "Interestingly, we demonstrated that inhibition of PKC and ROCK signaling blocked WNT5A-mediated MARCKS phosphorylation and melanoma cell invasion, which indicated that both PKC and RhoA-ROCK, as intermediate signaling pathways, are crucial during WNT5A-regulated MARCKS function." (PMID 32033033, 2020). "Furthermore, RHOA expression is also correlated with the absence of metastases and prolonged OS of melanoma patients." (PMID 33072757, 2020). "Other recent applications of intravital FRET investigating, for example, RhoA, intricate Erk signalling propagation events from in the skin or cancer stemness, PKA in vascular permeability and stromal targeting in melanoma could benefit from this approach." (PMID 29985127, 2018). "Thus, the contradictory results could be explained by the distinct methodological approaches and melanoma models used, and the absence of a clear distinction between the impact of RHOA expression on primary vs. metastatic melanoma." (PMID 33072757, 2020). "It remains unclear as to why DLC1 OE failed to inhibit RHOA activity in melanoma cells." (PMID 32214200, 2020). "Expression of PDZ-RhoGEF dominant negative mutants rescued invadopodia in PAK4-depleted melanoma cells, which suggests that a PAK4-mediated reduction in RhoA activity is required for invadopodium maturation." (PMID 32309283, 2020). "Conversely, we did not observe significant alteration of RHOA activity and its downstream events in both DLC1 KD and OE melanoma cells." (PMID 32214200, 2020). "While WT-DLC1 but not K714E-DLC1 reduced the levels of active RhoA-GTP in DU145 prostate cancer cells the levels of RhoA-GTP and p-MLC2 remained unaltered in melanoma cells treated with either WT-DLC1 or K714E-DLC1." (PMID 32214200, 2020). "Treatment of B16-F10 melanoma cells with LY294002, a PI3K inhibitor, strikingly induced RhoB, but not RhoA protein levels." (PMID 29385717, 2018). "One study demonstrated that over expression of RhoC in a radial growth phase melanoma cell line, WM35, promoted cell invasion and increased signaling through the PI-3K/Akt pathway, independent of signaling through the RhoA downstream effector ROCK." (PMID 19400942, 2009). "Surprisingly, in neither of these two studies did the authors explore the relationship between RhoA and PKC in terms of their activation of MARCKS nor their possible downstream effects on the invasion, migration and metastatic capacities of BRAFi-R melanoma cells." (PMID 36551563, 2022). "The observed membrane-expressed CD70 down-regulations induced by siRhoA2 transfection or U0126 treatment were not increased by the combination of both treatments, indicating that RhoA and MAPK pathway have no additive effects on the regulation of melanoma-expressed CD70." (PMID 26828592, 2016).
melanoma (continued). "In addition, the lack of increased RHOA activity in DLC1 KD melanoma cells could be due to predominant nuclear localization of endogenous DLC1, which was shown to be less efficient in mediating RHOA inhibition in other cancer cell types compared with cytoplasmic DLC1." (PMID 32214200, 2020).
lung cancer (93 papers, 2009 to 2025). A malignant neoplasm involving the lung. "RhoA is also implicated in mediating the activation of FAK in response to the development of aggressive non‐small cell lung cancer." (PMID 34528373, 2021). "Our study investigated the association between HSPs, RAC1 and RhoA and the survival time in Chinese lung cancer patients treated with platinum-based chemotherapy." (PMID 32848724, 2020). "As aPC is also known to promote lung cancer metastasis, we analyzed the possibility of RhoA-ROCKII axis in promoting aPC-induced release of EVs from human lung cancer cells." (PMID 41271627, 2025). "We also observed that the RhoA-ROCKII-JNK1/2-MLC2 pathway plays a major role in aPC-induced biogenesis of EVs in lung cancer cells." (PMID 41271627, 2025). "In lung cancer, Rho GTPases, especially RhoA, Rac1, and Cdc42, play key roles in tumor progression and metastasis." (PMID 39870629, 2025). "Hypoxia induces RHOA signaling in hepatocellular carcinoma and promotes vasculogenic mimicry, whereas in lung cancer, hypoxia facilitates RHOA-mediated aggressive cell motility." (PMID 40600795, 2025). "Earlier studies have indicated that the RhoA-ROCKII axis plays an important role in the metastasis of human lung cancer." (PMID 41271627, 2025). "In the study «Relationship between the expression of ARHGAP25 and RhoA in non−small cell lung cancer and vasculogenic mimicry» there were 130 patients." (PMID 40786517, 2025). "Overexpression of ALOX12 in lung cancer increases the activities of RhoA and NF-κB, which promotes cell proliferation and migration." (PMID 38719775, 2024). "Taken together, these results indicate that C. sinensis probably exerts a protective effect against NSCLC by suppressing the expression of the RhoA gene, then recruiting immune cells, enhancing immune function, and inhibiting lung cancer via the MAPK pathway." (PMID 38528546, 2024). "This was similar to the results of previous studies on apoptosis induced by RhoA knockdown in lung cancer cells and zebrafish embryogenesis." (PMID 37864185, 2023). "MALAT1 has been found to act as a ceRNA for miR‐185‐5p in lung cancer, and RhoA is a target gene of miR‐185 in human colorectal cells." (PMID 37395157, 2023). "Parallel to our findings with RhoA, vigilin IHC results clearly distinguish between MM and lung cancer." (PMID 36323745, 2022). "Specifically, RhoA activation stimulates downstream effectors and mediates Cofilin-dependent actin cytoskeleton reorganization in lung cancer cell migration." (PMID 35379791, 2022). "In the differential diagnosis of MM from lung cancer, the accuracy and specificity of RhoA, vigilin, and calretinin staining were almost equivalent." (PMID 36323745, 2022). "The myosin IXB (MYO9B) gene encodes an F-actin–based cytoskeletal motor protein, which has been reported to suppresses the RhoA activity in lung cancer cells." (PMID 36127319, 2022). "RhoA and SRF also control the expression of several drug resistance and metastasis-associated genes in EGFR-mutant lung cancer cells." (PMID 36509758, 2022). "In lung cancer, miR-26b inhibits the invasion and migration of cancer cells by directly targeting hENT1 depending on the RhoA/ROCK-1 signaling pathway." (PMID 35293283, 2022). "Upon JMJD8 knockdown in lung cancer cell lines, cyclin B1, RhoA, RhoC, MMP9, and N-cadherin were down-regulated, and p21 and E-cadherin were conversely up-regulated." (PMID 33442397, 2021). "Akt/mTOR and RhoA signaling pathway are both critical in lung cancer development, which are reported to be regulated by TNS1." (PMID 33269380, 2021). "ERK, c-Myc and RhoA are the genes playing vital roles in tumor metastasis of many cancers including lung cancer." (PMID 33858415, 2021). "PP2A has been shown to regulate RhoA in T cells, and Rac1 in lung cancer, implying SET-mediated regulation of PP2A in osteoclasts." (PMID 34884920, 2021). "The knockdown of RhoA as the member of the Rho family inhibits lung cancer cell proliferation and induces apoptosis." (PMID 33765916, 2021).